TTC9 (tetratricopeptide repeat domain 9)
Synonyms: KIAA0227; TTC9A
Tractability: PROTAC: its protein half-life has been measured.
Gene: Protein-coding gene on chromosome 14 (70,641,665 to 70,675,366, forward strand). Ensembl gene ENSG00000133985.
Subcellular location (Human Protein Atlas): Nuclear bodies
Genetic constraint (gnomAD): Loss-of-function variants: 13 observed, 22.35 expected, observed/expected ratio (o/e) 0.58, 90% interval 0.38 to 0.93. The upper end of that interval is the gene's LOEUF score, 0.93, which puts it in group 3 of 6, group 1 being the genes least tolerant of losing a copy. Missense variants: 278 observed, 260.6 expected, observed/expected ratio (o/e) 1.07, 90% interval 0.97 to 1.18. Synonymous variants: 148 observed, 118.74 expected, observed/expected ratio (o/e) 1.25, 90% interval 1.09 to 1.43.
Homologues: Orthologues: chimpanzee TTC9 (99% identical), macaque TTC9 (98% identical), rabbit TTC9 (95% identical), pig TTC9 (95% identical), rat Ttc9 (91% identical), dog TTC9 (90% identical), mouse Ttc9 (89% identical), guinea pig TTC9 (79% identical), tropical clawed frog ttc9 (64% identical), zebrafish TTC9 (55% identical), Caenorhabditis elegans fkb-4 (10% identical), Caenorhabditis elegans fkb-5 (10% identical). Paralogues in human: TTC9B (53% identical), TTC9C (36% identical), FKBP4 (18% identical), FKBPL (18% identical), FKBP5 (18% identical), FKBP6 (18% identical), FKBP8 (18% identical), FKBP9 (16% identical), FKBP15 (15% identical), FKBP10 (14% identical), FKBP1B (12% identical), FKBP7 (11% identical), and 6 more.
Diseases named in the same sentence as TTC9 in open-access papers:
TTC9 is named in the same sentence as 8 diseases in open-access papers, as found by Europe PMC text mining. Sharing a sentence is not in itself a finding about the gene and the disease. The quoted sentences say what the papers report.
Anxiety (2 papers, 2016 to 2022). Intense feelings of nervousness, tension, or panic often arise in response to interpersonal stresses. "The involvement of tetratricopeptide repeat domain 9A (TTC9A) in anxiety-like behaviors through estrogen action has been reported in female mice, this study further investigated its effects on social anxiety and aggressive behaviors." (PMID 35949301, 2022).
TTC9 also shares sentences with these, for which no sentence is quoted: anxiety disorder (1 paper); breast carcinoma (1); cancer (1); cervical tumors (1); gynecologic cancers (1); Hyperkeratosis (1); tumor (1).